NUP93 (nucleoporin 93)
Diseases named in the same sentence as NUP93 in open-access papers (continued):
Sharing a sentence is not in itself a finding about the gene and the disease.
cancer (6 papers, 2016 to 2025). A tumor composed of atypical neoplastic, often pleomorphic cells that invade other tissues. "Mechanistically, LIMK1 and CDK5 synergistically phosphorylate β‐catenin at S191, enhancing its phosphorylation and interaction with Nucleoporin 93, resulting in β‐catenin nuclear translocation and activation of key pathways in cancer metastasis." (PMID 40476449, 2025). "Our findings also shed light on the differences between primary human cells versus cancer cell lines, in the context of NUP93’s functions." (PMID 37853046, 2023). "The reduced proliferation was also confirmed in microfluidic invasion assay where NUP93 silenced BCCs not only migrated significantly less than control cells but also formed smaller micrometastases (i.e., cancer cell aggregates)." (PMID 31959624, 2020). "Silencing LIMCH1, a gene responsible for actin cytoskeleton remodeling and up-regulated upon Nup93 depletion, partially restored the invasive phenotype of cancer cells." (PMID 31959624, 2020). "All of the results suggest that MTs of ADPGK, PCGF6, PKP2, NUP93 and SLC22A5 can be the driver mutations controlling the cancer metastasis via affecting the EMT pathways where Snail, Claudin-1 or ZEB1 is involved." (PMID 27625789, 2016). "We identify driver mutations in ADPGK, NUP93, PCGF6, PKP2 and SLC22A5, which are verified to enhance cancer cell migration and prompt metastasis with in vitro experiments." (PMID 27625789, 2016).
infection (6 papers, 2018 to 2025). The state of being infected such as from the introduction of a foreign agent such as serum, vaccine, antigenic substance or organism. "We also determine the impact of the pathogenic variants on the three-dimensional (3D) structure of the nucleoporin 93 (NUP93) protein and the potential implications of the changes for the more common primary and infection-mediated cFSGS." (PMID 35874595, 2022). "In the present study, the expression of Nup93 was upregulated by 1.29-fold after GD178 infection at 12 h." (PMID 31592345, 2019). "The CsA dependence of HIV-1A92E infection in HeLa cells was exaggerated by some Nup knockdowns (e.g. NUP93, NUP205, NUP54, NUP153) while other knockdowns reduced or eliminated the enhancing effects of CsA (e.g. NUP98, NUP107, NUP155)." (PMID 30084827, 2018). "Additionally, the ability of MX2 to rescue HIV-1N57S infection from inhibition by CsA in HT1080 cells was reduced by NUP93 and NUP205 depletion." (PMID 30084827, 2018). "There were, however, a number of differences in Nup requirements for HIV-1WT infection in RANBP2∆Cyp cells, including a dramatic increase in sensitivity to NUP155 knockdown, and decreased sensitivity to NUP107, NUP93, and RANBP2 depletion." (PMID 39853118, 2025). "FIV infectivity and MX2 resistance were also unaffected by most Nup depletions in HT1080 cells, but a small number of knockdowns (NUP93, NUP205, NUP160) were significantly deleterious to FIV infection in HOS cells." (PMID 30084827, 2018). "Nup155 is a non-FG Nup in the Nup93-subcomplex that we previously noted N74D HIV-1 to be more dependent for infection than WT HIV-112." (PMID 37355754, 2023).
tumor (6 papers, 2018 to 2026). "Loss of Nup93 led to significant defects in tumor establishment/propagation in vivo, whereas patient samples revealed that high Nup93 and low LIMCH1 expression correlate with late tumor stage." (PMID 31959624, 2020). "Beyond that, NUP93 was found to be associated with tumor progression." (PMID 35211510, 2022). "In vivo, disruption of the NUP93/SOX2/G3BP1 axis suppressed tumor growth and synergized with gemcitabine." (PMID 41896201, 2026). "Overall, our data pointed towards a potential key role of Nup93 in tumor propagation." (PMID 31959624, 2020). "Finally, in vivo experiments and analysis of human biopsies confirmed the critical role of Nup93 in tumor propagation." (PMID 31959624, 2020). "The next predicted gene with differential APA patterns in different tumor types is NUP93." (PMID 32626751, 2020). "The mechanistic basis involves ARMC12, which functions within liquid-liquid phase-separated condensates to co-activate MYC, driving the subsequent up-regulation of NUP62, NUP93, and NUP98, elevation of NPC number, and tumor progression." (PMID 41510169, 2026). "Specifically, it reversed enhancement in tumor growth, mass, and expression of downstream genes (NUP62, NUP93, and NUP98), accompanied by modulation of NPC numbers and Ki-67 or CD31 labeling index." (PMID 41510169, 2026). "Instead, our data reveal that Nup93 is involved in the remodeling of the AC, which has consequences on the ability of the cells to invade through the ECM and contribute to the progression of the tumor." (PMID 31959624, 2020).
kidney disease (5 papers, 2021 to 2025). "In the case of kidney disease associated with NUP93, it seems therefore important to look for other abnormalities such as neurological features to answer the question of the phenotypic spectrum of NUP93 mutations." (PMID 41209161, 2025). "The compound heterozygous variants found in this family are located in the carboxyl terminus of the NUP93 protein, a region often associated with both kidney and non-kidney disease-causing variants." (PMID 35874595, 2022). "Genetic testing for hereditary renal disease of the patient revealed 2 novel heterozygous mutations in the Nucleoporin 93 (NUP93) gene, which were predicted pathogenic and harmful by bioinformatic softwares of SIFT, PolyPhen_2 and REVEL." (PMID 33578576, 2021). "Among these four genes, NCAPG, NUP93, and TOP2A were previously reported to be closely related to kidney disease, such as ccRCC." (PMID 35211510, 2022). "Among these four genes, NCAPG, NUP93, and TOP2A, were previously reported to be closely related to kidney disease." (PMID 35211510, 2022).
neurological diseases (2 papers, 2020 to 2024). "Interestingly, a subset of ASD-associated genes that were recovered after IGF-1 treatment has previously been linked to neurological disorders such as MFF, a mitochondrial gene that is associated with Leigh-like encephalopathy, and Nup93, a nucleoporin important in neuronal differentiation." (PMID 32591005, 2020).
heart (1 paper, 2012). "This study shows alterations in specific proteins (NDC1, Nup160, Nup153 and Nup93) that compose NPC in ischaemic and dilated human heart." (PMID 23152829, 2012).
NUP93 also shares sentences with these, for which no sentence is quoted: end-stage renal disease (2 papers); hepatocellular carcinoma (2); steroid-resistant nephrotic syndrome (2); bladder cancer (1); cardiovascular disease (1); coronary heart disease (1); cystic kidney disease (1); esophageal cancer (1); gastrointestinal disease (1); glioma (1); glomerulopathy (1); infantile bilateral striatal necrosis (1); kidney failure (1); nephritis (1); Nephropathy (1); Obstructive azoospermia (1); optic atrophy (1); primary biliary cirrhosis (1); rheumatic diseases (1); SARS-CoV Infections (1); schizophrenia (1); systemic lupus erythematosus (1).